PGP (phosphoglycolate phosphatase)
Diseases named in the same sentence as PGP in open-access papers (continued):
Sharing a sentence is not in itself a finding about the gene and the disease.
cancer (continued). "However, a major problem with cisplatin treatment is the development of acquired-drug resistance of the cancer cells involving increased MDR1/PgP activity." (PMID 20010943, 2010).
tumor (755 papers, 1991 to 2026). "Studies using multilayered cell cultures show that increased P-glycoprotein (PgP) is associated with better penetration of doxorubicin, while PgP inhibitors decrease drug penetration in tumor tissue." (PMID 19807929, 2009). "The effect could be explained by the fact that these polymorphisms cause an increase in glycoprotein P (PgP) expression with the increase in efflux of 5-fluorouracil from tumor cells." (PMID 38248103, 2024). "The three studies that used immunochemistry assays used different methodologies, and one study did not follow the guidelines agreed upon at the consensus meeting for immunohistochemical detection of PgP in human tumor tissue samples." (PMID 40667646, 2025). "Previous studies have shown that immunohistochemical analysis is superior to routine H&E assessment and it is recommended to use at least three immunohistochemical markers such as synaptophysin, chromogranin, PGP 9.5 and cyclin-D1 to demonstrate tumor tissue." (PMID 34558657, 2022). "Doxorubicin is a PgP substrate, that is efficiently pumped out of tumor cells where PgP is highly expressed." (PMID 19807929, 2009). "In the course of examining tumors for expression of neuroendocrine function, we surprisingly detected high amounts of PGP 9.5 positive cells mainly in tumor vasculature." (PMID 19551151, 2009). "Studies have revealed differences in drug distribution within ex vivo tumor tissue models containing cells expressing low levels of PgP and those with high PgP expression, and these distributions can be modified by PgP inhibitors." (PMID 19807929, 2009). "The PTP prodrug in combination with a high dose of conjugate (10 mg kg-1) gave the best anti-tumour activity despite being a 10-fold worse substrate for CPG2 than PGP." (PMID 7577451, 1995). "The evidence for sex, histologic subtype, tumor PgP expression, and LDH level was less clear." (PMID 40667646, 2025). "The tumor region on the H&E staining was also identified on the PGP immunostaining." (PMID 35565366, 2022). "The region marked as tumor on the H&E staining was identified on the PGP immunostaining as well." (PMID 34359564, 2021). "In oncology, PET imaging studies can provide valuable information on drug access to tumour tissue, which can be affected by a number of factors such as the P-glycoprotein (PgP) and breast cancer resistance protein (BCRP) drug efflux mechanisms and aberrant tumour vasculature." (PMID 25202719, 2014). "We hypothesized that BCMA-targeted BTZ nanotherapy would target the tumor tissue, amplify the anti-tumor effect and enhance the immune therapeutic efficacy of the free drug in the MM tumor microenvironment, as well as overcome PgP-mediated drug resistance, with minimal toxicity to normal cells." (PMID 38072962, 2023). "Drug distribution may be influenced in tumor tissue by the presence of high interstitial fluid pressure, an extensive extracellular matrix, cell-cell contact and the expression of efflux pumps such as PgP on the cell surface." (PMID 19807929, 2009). "Thus, in PgP overexpressing tumors there is less uptake and binding into proximal cells, resulting in a shallower gradient of decreasing doxorubicin fluorescence with increasing distance from tumor blood vessels." (PMID 19807929, 2009). "The expression of relevant molecular biomarkers of both tumor types, analyzed in all PDXs, was also faithfully mirrored by PDX, in particular SATB2 and PGP in OS PDX, CD99 and caveolin 1 in EW PDX." (PMID 31434953, 2019). "Co-expression of PGP 9.5, NSE, calretinin, and GFAP in the tumor cells and normal nerve cells was observed in all cases." (PMID 29329562, 2018). "PGP 9.5 is an immature neuroendocrine marker and a candidate tumor marker for human NSCLC where it is expressed in tumor cells from >70% of stage II and IIIA tumors." (PMID 19551151, 2009).
tumor (continued). "Doxorubicin fluorescence intensity in the first 10 μm from blood vessels is significantly greater in PgP overexpressing tumors that were pretreated with verapamil and PSC 833 in the murine tumor model, and with PSC 833 in the xenograft model." (PMID 19807929, 2009). "Finally, we demonstrate that PgP/pHSV-TK with GCV treatment increases the suicide effect and apoptosis of tumor cells and reduces tumor size in a rat T5 SCT model." (PMID 30965667, 2019). "Additionally, PGP 9.5, a marker for immature neuroendocrine cells as well as a candidate tumor marker for NSCLC, were expressed in the tumor." (PMID 29464089, 2018). "Furthermore, the tumor cells and normal nerve cells exhibited co-expression of nerve markers PGP 9.5, NSE, calretinin, and GFAP, suggesting that the nervous system plays a role in the development of this tumor." (PMID 29329562, 2018). "Moreover c-MYC induces production of VEGF by tumor cells leading to tumor vascularisation with unusual vessels that are mosaics containing PECAM-1 positive and PGP 9.5 positive endothelial cells." (PMID 19551151, 2009). "Modeling from this data by removing noise from neighboring vessels suggests that the use of potent PgP inhibitors, such as PSC 833 might lead to a paradoxical decrease in the uptake of doxorubicin in tumor cells situated more distant from tumor blood vessels." (PMID 19807929, 2009). "Moreover, derivatives may constitute the substrate for glycoprotein P (PGP) that belongs to ABC-transporters that restrict the compounds from entering the central nervous system and are involved in tumor multidrug resistance." (PMID 35682571, 2022). "Moreover, this graph shows that the submitted compounds were not P-glycoprotein substrates (PGP-), and not amenable to the efflux system effected by this transporter, which is utilized by numerous tumor cells lines as a drug-resistance mechanism." (PMID 34832895, 2021). "The PgP inhibitors did not modify growth delay for either type of tumor." (PMID 19807929, 2009).
infection (27 papers, 2005 to 2025). The state of being infected such as from the introduction of a foreign agent such as serum, vaccine, antigenic substance or organism. "In order to assess the impact of the nanomaterials on intestinal histopathological changes induced by the infection, parameters such as the inflammatory infiltrate, the amount of immunoreactive neurons for PGP 9.5 and collagen deposition were evaluated." (PMID 39598539, 2024). "During head infection assays, we noted that EU07 has PGP activity." (PMID 35956478, 2022).
PGP also shares sentences with these, for which no sentence is quoted: ovarian carcinoma (115 papers); leukemia (112); lung carcinoma (65); gastric cancer (60); hepatocellular carcinoma (54); glioblastoma (42); prostate carcinoma (41); brain tumors (33); Alzheimer disease (31); non-small cell lung carcinoma (29); lymphoma (28); chronic myeloid leukemia (20); melanoma (19); Stroke (19); adenocarcinoma (16); neurological disorders (16); neurodegenerative disease (15); acute lymphoblastic leukemia (14); breast tumor (14); multiple myeloma (14); pancreatic cancer (14); bladder cancer (12); rheumatoid arthritis (11); sarcoma (11); status epilepticus (11); colorectal adenocarcinoma (10); epidermoid carcinoma (10); Obesity (10); renal carcinoma (10); amyotrophic lateral sclerosis (9).
A further 311 diseases each share a sentence with PGP in 9 papers or fewer.